CDK8 (cyclin dependent kinase 8)
Diseases named in the same sentence as CDK8 in open-access papers (continued):
Sharing a sentence is not in itself a finding about the gene and the disease.
pancreatic cancer (12 papers, 2015 to 2024). "The high expression level of CDK8 in pancreatic cancer was considerably associated with poor prognosis." (PMID 37807067, 2023). "In a related example, the positive regulation of angiogenesis by CDK8 was previously suggested in pancreatic cancer." (PMID 38546787, 2024). "CDK8 induces the β-catenin expression in pancreatic cancer that enters into the nucleus to mediate the activation of angiogenesis-promoting transcription factors." (PMID 37807067, 2023). "Studies on ovarian and pancreatic cancer cell lines have provided further evidence of a correlation between EMT-associated transcription factors and the expression of CDK8/CDK19." (PMID 31248103, 2019). "Based on work in a pancreatic cancer model, CDK8 has been proposed to have a role in the epithelial-to-mesenchymal transition (EMT)." (PMID 31248103, 2019). "Finally, we tested the combination of ERK and CDK8/19 inhibition in a well-credentialed, orthotopic, syngeneic mouse model of pancreatic cancer." (PMID 38822082, 2024). "Angiogenesis is further influenced by CDK8, which has been found that when overexpressed, it promotes angiogenesis in pancreatic cancer via activation of CDK8/β-catenin/KLF2 signalling, while silencing of CDK8 inhibits angiogenesis in pancreatic cancer in vitro and in nude mice xenograft models." (PMID 30340359, 2018). "In studies of pancreatic cancer, CDK8 was found to activate the expression of factors critical for stimulating the EMT process (Snail1 and ZEB1) through the Wnt/β-catenin signaling pathway and to increase the invasion and migration of pancreatic cancer cells." (PMID 38460002, 2024).
gastric cancer (9 papers, 2014 to 2024). A primary or metastatic malignant neoplasm involving the stomach. "CDK8 levels and their association with β-catenin delocalization have also been associated with poor prognosis of gastric cancer in a study involving patient tissues and gastric cancer cell lines." (PMID 36769170, 2023). "Recent evidence supports the idea that mediator complex-associated CDK8/CycC has been involved in the regulation of multiple transcription pathways and implicated as an oncogene in colorectal and gastric cancers through activation of WNT signaling." (PMID 32206448, 2020). "Different human malignancies, mainly colorectal and gastric cancers, were produced as a result of overexpression of CDK8/CycC in the mediator complex." (PMID 32206448, 2020). "CDK8 is an oncogene in colorectal and gastric carcinoma with differentially expressed genes from animal PRL-PT models showing enrichment for CDK8 targets." (PMID 32201880, 2020). "Amplification dependent and independent overexpression of the human Mediator Cdk8 kinase subunit, or other members of the Cdk8 module, occurs in a large percentage (>50%) of colon, breast, and gastric cancers and is proposed to act as an oncogene." (PMID 27741243, 2016). "Moreover, miR-107 also targets CDK8 in gastric cancer cells at its 3′UTR site and regulates the mRNA levels of CDK8." (PMID 36769170, 2023). "Meanwhile, hsa-miR-26b-5p directly interacts with PDE4B and CDK8, thereby downregulating STAT3 phosphorylation and nuclear translocation, and promoting gastric cancer cell proliferation." (PMID 38796629, 2024).
lung carcinoma (8 papers, 2010 to 2025). "This suggests that elemene can prevent chemoresistance in lung cancer by inhibiting CDK8-regulated P21-mediated paracrine activities." (PMID 34641334, 2021). "Recent reports indicate that CDK8 inhibition enhances the anti-cancer effects of MEK inhibitors, and in EGFR mutant lung cancer, the combination of EGFR inhibitors with YAP/TEAD inhibitors has shown synergistic effects." (PMID 40833497, 2025). "The expression of CDK8 and SUB1 was also higher in lung cancer patients with high HIF1α expression, further suggesting the upregulation of CDK8 and SUB1 by hypoxic stress." (PMID 34362882, 2021). "The high expression of CDK8 and SUB1 was correlated with the poor survival of patients with lung cancer." (PMID 34362882, 2021). "In lung cancer, miR-138-5p inhibition could promote carcinogenesis and progression by targeting E2F3, CDK8, ZEB2, PD-L1, and PD-1, and the present results displayed that miR-138-5p is downregulated in LUSC tissues and cells." (PMID 35635595, 2022). "To verified which gene(s) can be targeted by miR-26a-5p, we overexpressed miR-26a-5p in H1299 cells and found that only PTEN expression was decreased and CDK8 and PTGS2 expression did not change in H1299 cells, implying that only PTEN may be a target of miR-26a-5p in lung cancer." (PMID 33407724, 2021).
hepatocellular carcinoma (6 papers, 2010 to 2025). A malignant tumor that arises from hepatocytes. "Silencing of HEIH in a hepatocellular carcinoma xenograft model hindered cell viability, migration, and invasion by regulating the miR-193a-5p/CDK8 axis." (PMID 40161373, 2025). "We found that expression of CDK8 is upregulated during DENV2 infection of Huh7 human hepatocellular carcinoma cells, and that this precedes increased expression of two key genes, hexokinase 2 (HK2) and microtubule-associated protein 1 light chain 3 (LC3)." (PMID 32560467, 2020). "Further studies revealed that long non-coding RNA (lncRNA) in silenced hepatocellular carcinoma (HEIH) could bind to miR-193a-5p to promote the expression of cyclin-dependent kinase 8 (CDK 8) in hepatocellular carcinoma (HCC) cells." (PMID 40161373, 2025). "It is worth noting that miR-26a could suppress MYC by targeting the Wnt pathway coactivator, cyclin-dependent kinase 8 (CDK8), to inhibit progression and metastasis of hepatocellular carcinoma." (PMID 35120580, 2022). "Here, we show that expression of CDK8, but not CDK19, is increased during dengue virus infection in Huh7 human hepatocellular carcinoma cells, although both are required for efficient viral replication." (PMID 32560467, 2020).
metastatic tumors (6 papers, 2022 to 2025). "While most of our results align with existing studies, the unique identification of mutations such as SAMD9L and ATP8B1 in metastatic tumors and gender-specific enrichment of CDK8 and EPHB2 are less commonly reported and may represent new areas for investigation in personalized therapeutics." (PMID 41590495, 2025). "Treatment with either CDK8/19i significantly increased mouse survival of the metastatic disease (Right), with SNX631 exerting a stronger effect in agreement with its greater potency." (PMID 39541354, 2024). "However, the frequency of CDK8 gene amplification is highest in CRPC compared to other cancers and is associated with increased expression of CDK8 in metastatic disease [,83]." (PMID 40163908, 2025). "In summary, our results warrant the exploration of CDK8/19i for the treatment of TNBC, both as single agents, with activity against the metastatic disease, and as combinations with approved drugs, in particular mTOR and AKT inhibitors." (PMID 39541354, 2024). "Although the primary tumor growth of murine 4T1 cells was not significantly affected by CDK8/19i, Cdk8 knockdown in tumor cells and SNX631 treatment of mice carrying established lung metastases extended the survival of the metastatic disease in this model." (PMID 39541354, 2024).
glioma (5 papers, 2018 to 2023). A benign or malignant brain and spinal cord tumor that arises from glial cells (astrocytes, oligodendrocytes, ependymal cells). "c-Myc reportedly contributes to the glioma cell proliferation via c-Myc-LPP-AS2 axis, promotes glioma stem cell formation via CDK8-regulated c-Myc expression, and enhances migration as well as angiogenesis via c-Myc-microRNA-9 axis." (PMID 36499054, 2022). "The results also demonstrated that knockdown of CDK8 suppressed glioma cell proliferation by inducing G1-S phase arrest and cell apoptosis." (PMID 30524203, 2018). "In this study, we found that CDK8 was overexpressed in glioma compared with the level in normal tissues, which revealed an inverse correlation between CDK8 mRNA expression and miR-770 expression in glioma tissues." (PMID 30524203, 2018). "miR-770 inhibits glioma cell proliferation and induces apoptosis through suppression of the Wnt/β-catenin signaling pathway by targeting CDK8." (PMID 30524203, 2018). "After cotransfection with the miR-770 and CDK8 vectors, we found that the overexpression of CDK8 counterbalanced the tumor suppressor effect of miR-770 in glioma cells during cell proliferation." (PMID 30524203, 2018). "Our results showed that the expression of CDK8 was significantly upregulated at both the mRNA and protein levels in glioma tissues compared to that in adjacent normal tissues (p< 0.01)." (PMID 30524203, 2018). "Our study demonstrates that miR-770 inhibits glioma cell proliferation and G1-S transition and induces apoptosis through suppression of the Wnt/β-catenin signaling pathway by targeting CDK8." (PMID 30524203, 2018). "We recently identified 4-acetyl-3-{4-[2-(tetrahydropyran-4-yloxy)ethoxy]phenoxy}benzamide (hereafter referred to as KY-065) as a novel potential CDK8 inhibitor, which inhibits the stemness and tumorigenicity of glioma stem cells, thus exerting anti-glioblastoma potential in vivo." (PMID 35777359, 2022). "MiR-770 by targeting CDK8 could inhibit glioma cell proliferation and cell cycle G1/S transition and induce apoptosis via suppressing Wnt/β-catenin signaling." (PMID 33330110, 2020). "Moreover, we found that the overexpression of CDK8 counterbalanced the tumor suppressor effect of miR-770 in glioma cells." (PMID 30524203, 2018). "We provide evidence that miR-770 induces glioma cell apoptosis through targeting CDK8." (PMID 30524203, 2018). "miR-770 expression was inversely correlated with CDK8 expression in glioma tissues." (PMID 30524203, 2018). "Since miR-770 regulated cell proliferation, the cell cycle and apoptosis in glioma cells, CDK8 was validated as a direct target of miR-770, therefore, CDK8 was knocked down in glioma cells by RNA interference to validate its involvement in the tumor suppressor functions of miR-770." (PMID 30524203, 2018). "The expression of CDK8 was detected by qRT-PCR and Western blotting in glioma tissues." (PMID 30524203, 2018). "Importantly, CDK8 silencing recapitulated the cellular and molecular effects observed upon miR-770 overexpression, and CDK8 overexpression eliminated the effects of miR-770 overexpression on glioma cells." (PMID 30524203, 2018). "In addition, our results showed that cyclin-dependent kinase 8 (CDK8) was overexpressed in glioma tissues." (PMID 30524203, 2018). "Furthermore, CDK8 overexpression eliminated the effects of miR-770 overexpression on glioma cells." (PMID 30524203, 2018).
leiomyoma (5 papers, 2020 to 2026). A well-circumscribed benign smooth muscle neoplasm characterized by the presence of spindle cells with cigar-shaped nuclei, interlacing fascicles, and a whorled pattern. "Although MED12 exon 2 mutations and CDK8 activity have been reported in leiomyoma cells and tissues, this is the first report clarifying their association with patient treatment history." (PMID 41493967, 2026). "CDK8 was co-immunoprecipitated from leiomyoma tissue extracts using MED12 antibody to test its kinase activity in vitro, and the amount of phosphorylated substrate was measured." (PMID 41493967, 2026). "CDK8 inhibitors are recently developed anti-cancer drugs with the potential to inhibit leiomyoma growth." (PMID 41493967, 2026). "Cell proliferation and apoptosis of primary cultured MED12 wild-type leiomyoma cells were evaluated in the presence of a CDK8 inhibitor and sex steroid hormones." (PMID 41493967, 2026). "We aimed to clarify the relationship between MED12 mutation status, response to gonadotropin-releasing hormone (GnRH) agonist treatment, and CDK8 activity in leiomyomas." (PMID 41493967, 2026). "To determine the optimal CDK8 inhibitor concentration, we first tested various concentrations of Senexin A and Senexin B for their growth inhibitory effects in primary cultured leiomyoma cells." (PMID 41493967, 2026). "In the absence of GnRH treatment, MED12 WT leiomyomas exhibited significantly higher CDK8 activity than MED12 MUT leiomyomas (p = 0.02, Kruskal–Wallis test with Dunn’s post-hoc analysis)." (PMID 41493967, 2026). "We, therefore, explored CDK8 as a therapeutic target and investigated its activity in leiomyoma in relation to MED12 status and sex steroid hormone kinetics using clinical samples." (PMID 41493967, 2026). "We aim to address these limitations and evaluate the efficacy of CDK8 inhibitors in a mouse leiomyoma xenograft model in future studies." (PMID 41493967, 2026). "In contrast, in CDK8, the Z-score for leiomyoma-specific H3K27ac regions is higher than in normal tissue but remains below the randomization mean." (PMID 40345582, 2025). "In addition, although our analysis focused on ER expression in relation to CDK8 activity, the progesterone receptor (PR) also plays a key role in leiomyoma growth." (PMID 41493967, 2026). "This prompted us to consider a similar effect of CDK8 inhibition in leiomyomas." (PMID 41493967, 2026). "MED12 MUT leiomyomas have been reported to be highly responsive to ulipristal acetate treatment, and if CDK8 inhibitors prove effective for MED12 WT leiomyomas, they may facilitate precision medicine approaches." (PMID 41493967, 2026). "Previous studies have shown that PR signaling is particularly activated in MED12 MUT leiomyomas and CDK8 inhibition may influence PR expression or activity in MED12 WT leiomyomas." (PMID 41493967, 2026). "Rather, our results show that changes in the CDK8 submodule cistrome are positively correlated with altered H3K27Ac, suggesting that altered CDK8 binding is more consistent with general changes in the enhancer landscape of leiomyoma cells." (PMID 32094355, 2020). "However, 18% (n = 5409/30,697) of CDK8 submodule binding sites show changes in binding affinity in leiomyoma tissue samples as compared to myometrium." (PMID 32094355, 2020). "Together, these results establish that global loss of CDK8 chromatin binding is not an epigenetic feature of MED12 mutant leiomyomas." (PMID 32094355, 2020). "Therefore, CDK8 inhibitors could offer significant benefits in managing both leiomyoma growth and osteoporosis." (PMID 41493967, 2026). "Therefore, MED12 mutation-driven leiomyoma disease pathogenesis is more likely a result of CDK8 kinase activity defects, and not cyclin C-CDK8 binding defects, and future work will be required to identify the kinase substrate of the CDK8 submodule." (PMID 32094355, 2020). "Therefore, CDK8 inhibitors may also be available for the treatment of leiomyomas." (PMID 41493967, 2026).
leiomyoma (continued). "MED12 wild-type leiomyoma cells without GnRH agonist treatment showed high CDK8 activity, and inhibition of CDK8 activity suppressed cell growth in vitro." (PMID 41493967, 2026). "Because we corrected for the concentration of total extracted protein, it is possible that leiomyomas with a low percentage of nuclei had lower CDK8 activity, but we did not exclude cases because this reflects the true CDK8 activity of the leiomyoma." (PMID 41493967, 2026). "Although the mechanism by which decreased CDK8 activity suppresses leiomyoma growth remains unclear, this study revealed a GnRH agonist-induced reduction in MED12-dependent CDK8 activity." (PMID 41493967, 2026). "Therefore, we calculated the exclusive leiomyoma and normal myometrium peaks for H3K27ac, MED12, and CDK8." (PMID 40345582, 2025). "MED12 mutation-negative leiomyomas display copy number alterations in several other mediator complex subunits, such as MED18, MED8, CDK8, and the long non-coding RNA, RNA340 (CASC15)." (PMID 38279317, 2024). "Thirty thousand six hundred and ninety-seven genomic sites co-bound by CDK8 and MED12 were identified in myometrium and leiomyoma tissue samples, with hierarchical clustering analysis revealing tissue-type-specific CDK8 submodule occupancy in myometrium and leiomyoma." (PMID 32094355, 2020). "Of the 44 leiomyomas tested, 11 MED12 wild-type leiomyomas without preoperative GnRH agonist treatment had significantly higher CDK8 activity than nine GnRH agonist-treated MED12 wild-type leiomyomas and 15 leiomyomas with MED12 mutations without GnRH agonist treatment." (PMID 41493967, 2026).
osteosarcoma (4 papers, 2017 to 2023). A usually aggressive malignant bone-forming mesenchymal neoplasm, predominantly affecting adolescents and young adults. "Our findings indicated that repression of CDK8 led to a significant reduction in the proliferation, colony formation, and migration of osteosarcoma, chondrosarcoma, and antler cartilage cells." (PMID 37446017, 2023). "We discovered that osteosarcoma cells (SJSA) are naturally depleted of CDK8 protein." (PMID 28416637, 2017). "CDK8, EEF1A1, and NTN1 have been confirmed as direct target genes of miR-PC-2869 in osteosarcoma cells, and their involvement in the pathogenesis of various human cancers has been previously reported." (PMID 37446017, 2023). "In osteosarcoma cells that do not express CDK8, knockdown of CDK19 resulted in reduced proliferation, accompanied by reduced mitotic gene expression." (PMID 30693281, 2018). "SJSA cells, an osteosarcoma cell line, contain CDK19, but the CDK8 protein is almost undetectable." (PMID 28416637, 2017). "Thus, we hypothesized that CDK8, EEF1A1, and NTN1 mediate the tumor-suppressor activity of miR-PC-2869 in osteosarcoma cells." (PMID 37446017, 2023).
triple-negative breast carcinoma (4 papers, 2020 to 2026). An invasive breast carcinoma which is negative for expression of estrogen receptor (ER), progesterone receptor (PR), and human epidermal growth factor receptor 2 (HER2). "We continue to investigate the contributions of E2F1 and STAT3 to CDK8 inhibitor effects on triple-negative breast cancer cell line MDA-MB-468, and will report our results in due course." (PMID 41596544, 2026). "In this report, we communicate the results of our continuing investigation into the effects of CDK8 inhibitor on triple-negative breast cancer cell line MDA-MB-468." (PMID 41596544, 2026). "Previously, we demonstrated that the triple-negative breast cancer cell line MDA-MB-468 exhibited reduced cell viability and active apoptosis after treatment with a CDK8 inhibitor." (PMID 41596544, 2026). "In summary, we have demonstrated some of the effects of CDK8 inhibition on CDK8, E2F1, STAT3, and Mcl-1 proteins in MDA-MB-468 triple-negative breast cancer cells." (PMID 41596544, 2026).
Uterine leiomyoma (4 papers, 2015 to 2026). The presence of a leiomyoma of the uterus. "We also examined the effects of CDK8 inhibitors on primary cultured uterine leiomyoma cells." (PMID 41493967, 2026). "Rather, alterations in enhancer chromatin state, characterized by changes in H3K27Ac signal, promoter contact strength, and altered AP-1 complex/CDK8 submodule chromatin binding, together may account for dysregulated gene expression in uterine leiomyomas." (PMID 32094355, 2020).
acute lymphoblastic leukemia (3 papers, 2015 to 2025). Leukemia with an acute onset, characterized by the presence of lymphoblasts in the bone marrow and the peripheral blood. "A previous study established a correlation between CDK8 and the mTOR pathway in acute lymphoblastic leukemia, suggesting that CDK8 regulates protein synthesis not only within a subset of MB but also in other types of cancer." (PMID 39574899, 2024). "A small molecule that combines mTOR inhibition and degradation of CDK8 (YKL-06-101) induced cell death in human leukemic cells, representing a potential therapeutic strategy for treating acute lymphoblastic leukemia (ALL) patients." (PMID 39800748, 2025).
chronic myeloid leukemia (3 papers, 2021 to 2025). "In the culture of chronic myeloid leukemia cells, senexin Bincreased the antitumor effect of targeted inhibitors of chimeric tyrosinekinase Bcr-ABL, thus broadening thepossibilities of CDK8/19 inhibition in the therapy of blood cancers." (PMID 33959383, 2021).